DLC1 (DLC1 Rho GTPase activating protein)
Diseases named in the same sentence as DLC1 in open-access papers (continued):
Sharing a sentence is not in itself a finding about the gene and the disease.
leukemia (2 papers, 2017 to 2018). A malignant (clonal) hematologic disorder, involving hematopoietic stem cells and characterized by the presence of primitive or atypical myeloid or lymphoid cells in the bone marrow and the blood. "Using RNA sequencing, we found that genes associated with AML subtypes, such as RYR3, RHAG, PCDH9, ANK1, ADAMTS3, and DLC1, were significantly up-regulated in the leukemia cells of two responders, but not in the 3 non-responders." (PMID 28900115, 2017).
meningioma (2 papers, 2016 to 2020). A generally slow growing tumor attached to the dura mater. "Results indicate that isoform 1 represents the main pool of DLC1 protein in meninges and its downregulation in meningiomas is associated with hypermethylation of CpG dinucleotides within the corresponding promoter region." (PMID 27614886, 2016). "The DLC1 variant 1 was also the only one to be significantly down-regulated in meningiomas compared to meninges (6.5 fold change of expression p = 0.004), however, a small but insignificant decrease of DLC1-v5 expression was also observed." (PMID 27614886, 2016). "An interesting finding was a recurrent gain of 8p22 observed only in grade I meningiomas, a region which includes DLC1, a suppressor candidate gene probably implicated in the developments or progression of meningiomas, usually found deleted, when related to CNAs." (PMID 32670372, 2020). "Interestingly, this region is usually related to loss, as it harbors DLC1, a suppressor candidate gene probably implicated in the developments or progression of meningiomas." (PMID 32670372, 2020). "Since it has been previously shown that DLC1 transcription variants are expressed in a tissue-dependent manner, we designed different sets of PCR primers specific for particular transcripts to measure their expression in normal meninges and meningiomas with qRT-PCR." (PMID 27614886, 2016). "DLC1 expression levels are significantly downregulated in meningiomas compared to normal meninges, whereas they are comparable in benign and atypical/anaplastic tumors." (PMID 27614886, 2016). "DLC1 downregulation in meningiomas was reported once in a study on a small series of samples; 6 tumor samples and 4 normal meninges, however, no DNA methylation of the gene promoter have been found." (PMID 27614886, 2016). "DLC1 was found in 200 genes most differentially expressed in meningiomas and normal meninges in both datasets." (PMID 27614886, 2016). "We selected 18 meningioma tissue samples (4 meningothelial, 4 fibrous, 5 atypical and 6 anaplastic meningiomas) for immunohistochemical staining to detect DLC1 protein expression using a polyclonal antibody." (PMID 27614886, 2016). "The comparison of meningioma vs. normal meningeal tissue showed significantly higher DNA methylation in tumors at 6 probes clustered at the DLC1-v1 alternative promoter." (PMID 27614886, 2016). "Additional comparison of mRNA expression levels of all known DLC1 isoforms showed that DLC1-v1 is the one most expressed in normal meninges and its expression level is most notably reduced in meningiomas." (PMID 27614886, 2016). "In turn, DLC1-v1 that is fully active protein, significantly downregulated in meningiomas turns out to be the most relevant form of DLC1 protein in neoplastic transformation of meninges." (PMID 27614886, 2016). "This antibody was produced using immunogen peptide corresponding to N-terminal region of DLC1-v1 and thus it is specific for two isoforms that originate from the promoter region that we found as hypermethylated in meningiomas: DLC1-v1 and DLC1-v3." (PMID 27614886, 2016). "When DLC1 promoter methylation was matched with expression status, 3/4 expression positive meningiomas showed methylation levels around 50 % or less, whereas 13/14 negative tumor expression showed at least 70 % DNA methylation." (PMID 27614886, 2016). "A search of deposited microarray expression results also showed decreased DLC1 levels in meningiomas compared to normal meninges in different publicly accessible datasets." (PMID 27614886, 2016). "In our study, we identified DLC1 as being frequently hypermethylated in meningiomas from genome-wide comparisons of different meningiomas and normal meninges sections." (PMID 27614886, 2016). "mRNA expression levels of 5 isoforms of DLC1 transcript were measured in an additional series of meningiomas and normal meninges." (PMID 27614886, 2016).
meningioma (continued). "Downregulation of DLC1 in meningiomas was previously shown in a small study on 6 tumor samples." (PMID 27614886, 2016). "Importantly, this gene acts as a tumor suppressor and the transfection of primary meningioma cultured cells with normal DLC1 results in a decrease of meningioma cell growth." (PMID 27614886, 2016). "It is also known that DLC1 mutations have not been identified in meningiomas for whole exome sequencing studies and no mutations of this gene have been reported in the COSMIC database." (PMID 27614886, 2016). "High DNA methylation was associated with lack of DLC1 protein expression in meningiomas as determined by immunohistochemistry." (PMID 27614886, 2016). "Importantly, tumor and meninges samples revealed significantly different signal for the 220511_s_at probeset that cover only the mRNA transcripts originated from the alternative promoter region of DLC1-v1/-v3, that is commonly hypermethylated in meningiomas." (PMID 27614886, 2016). "Meningioma samples had slightly variable expression levels of DLC1 isoforms 1, 2 and 3, with an approximately twofold lower expression of DLC1-v2 compared to DLC1-v1 and DLC1-v3, but with an apparently lower RNA expression level of DLC1-v5 (p < 0.0001, Kruskal–Wallis test)." (PMID 27614886, 2016). "Interestingly, in line with the observation of the aberrant DLC1 expression in meningiomas, both focal adhesion and adherence junction formation processes were found among the most disturbed in meningioma pathogenesis and progression." (PMID 27614886, 2016). "Significantly higher methylation levels of this region was observed in meningiomas without DLC-1 protein expression compared to immunoreactive tumors." (PMID 27614886, 2016). "In contrast to the lack of reported DLC1 promoter methylation in meningiomas, we identified 5′ region of DLC1 as being frequently hypermethylated in this tumor." (PMID 27614886, 2016). "Interestingly, a previous study on DLC1 downregulation in meningiomas demonstrated a lack of promoter DNA hypermethylation in tumors." (PMID 27614886, 2016).
metastatic melanoma (2 papers, 2020 to 2022). A melanoma that has spread from its primary site to another anatomic site. "Previous study reported the association between decreased expression of cytoplasmic DLC1 and worse OS in metastatic melanoma." (PMID 35433689, 2022).
multiple myeloma (2 papers, 2012 to 2018). "Deregulation of DLC1 by DNA methylation is likely to be important in the pathogenesis of multiple myeloma by altering signaling associated with Rho-GTPases, which impacts cytoskeletal architecture and cellular motility." (PMID 23285118, 2012). "In MM, previous studies have shown methylation and inactivation of DLC1 in a high frequency of myeloma cell lines." (PMID 23285118, 2012). "Indeed, re-expression of DLC1 in MM has been shown to inhibit myeloma cell migration." (PMID 23285118, 2012).
nasopharyngeal carcinoma (2 papers, 2013 to 2016). A carcinoma arising from the nasopharyngeal epithelium. "DLC-1 (Loss of deleted in liver cancer-1) induced mitochondrial apoptosis, and inhibited EMT in nasopharyngeal carcinoma by targeting the EGFR/Akt/NF-κB pathway." (PMID 26636541, 2016).
Serous Ovarian Cancer (2 papers, 2015 to 2020). "The most frequently hypermethylated genes in stromal progenitor cells from ascites and corresponding bulk tumor tissues from the patients with serous ovarian cancer at an advanced stage were CDKN2B, RASSFIA, DLC1, and CCND2." (PMID 26597084, 2015).
thyroid cancer (2 papers, 2017 to 2022). "The analysis displayed that DLC1 expression significantly declined in normal controls in thyroid carcinoma." (PMID 35223504, 2022).
adenoma (1 paper, 2013). A neoplasm arising from the epithelium. "When methylation level higher than >1% was considered methylation positive, DLC-1 methylation was observed in 5/48 (10%) of normal mucosa, 26/57 (46%) of adenomas, and 48/80 (60%) of CRCs." (PMID 23509688, 2013). "In this study, we used MS-HRMA to detect DLC-1 promoter methylation in 48 normal mucosa, 57 adenomas, 80 CRC tissue samples, and 4 CRC cell lines." (PMID 23509688, 2013). "In addition, by quantifying the methylation status in DLC-1 promoter, we also found an accumulation of aberrant methylation following the adenoma-carcinoma sequence." (PMID 23509688, 2013). "When we examined the association of KRAS mutations to DLC-1 methylation, a statistically significant correlation was observed only in the CRCs (P = 0.010), but not in adenomas (P = 0.889)." (PMID 23509688, 2013). "In this study, we confirmed that the extensive DLC-1 methylation was associated with the KRAS mutations in CRCs but not in adenomas." (PMID 23509688, 2013). "Of the 57 adenomas and 80 CRC tissues, DLC-1 mRNA was downregulated in 30/57 (52%) and 63/80 (79%) samples, respectively." (PMID 23509688, 2013). "We found the methylation of DLC-1 promoter more frequently methylated in the CRC samples (C1, 60% and C2, 31%) than in the adenomas (A1, 9% and A2, 4%)." (PMID 23509688, 2013). "Five CRCs and five adenoma samples that were identified by MS-HRMA as extensive methylation and partial methylation, respectively, and two normal mucosa tissue samples were amplified with a 292 bp fragment in the DLC-1 promoter, covering 35 CpG sites." (PMID 23509688, 2013). "However, methylation and mRNA expression status of DLC-1 and its role in the adenoma-carcinoma progression have not been defined." (PMID 23509688, 2013). "Moreover, the transcriptional regulation of DLC-1 gene expression through epigenetic mechanisms has not been investigated in the normal adenoma-carcinoma sequence." (PMID 23509688, 2013).
angiosarcoma (1 paper, 2024). A malignant tumor arising from the endothelial cells of the blood vessels. "Angiosarcoma, an endothelial-derived form of cancer, is characterized by perturbed angiogenesis and the loss of DLC1." (PMID 38563084, 2024). "DLC1-deficient angiosarcoma cells in tumors display increased nuclear YAP levels." (PMID 38563084, 2024).
Ascites (1 paper, 2013). Accumulation of fluid in the peritoneal cavity (between the layers of the peritoneum that lines the abdomen). "In addition, DLC1 was also related with ascites, and PAI-1 was related with histological differentiation." (PMID 23988121, 2013).
cervical cancer (1 paper, 2008). A primary or metastatic malignant neoplasm involving the cervix. "We observed conspicuous phospho-MLC2 staining at the cell cortex in SMMC-7721, BEL7402, and WRL HCC cell lines, and HeLa cervical cancer cell line, which had no expression of DLC1." (PMID 18648664, 2008).
choriocarcinoma (1 paper, 2012). An aggressive malignant tumor arising from trophoblastic cells. "Loss of the 8p23.3p12 region, previously reported in primary choriocarcinoma, harbored (i) the CTSB gene, a cathepsin implicated in invasion and metastasis and (ii) DLC1 and TUSC3, two tumor suppressor genes that are expressed in the placenta, and often deleted in many cancers." (PMID 22253721, 2012).
cutaneous melanoma (1 paper, 2020). A primary melanoma arising from atypical melanocytes in the skin. "These expression analyses suggest that elevated levels and strong nuclear localization of DLC1 are associated with cutaneous melanomas." (PMID 32214200, 2020). "Analysis of the TCGA dataset showed higher levels of DLC1 transcripts in cutaneous melanoma (n = 461) than normal tissue samples (n = 558)." (PMID 32214200, 2020).
cystic kidney disease (1 paper, 2025). A congenital or acquired kidney disorder characterized by the presence of renal cysts. "Seven genes (3%) had no entries in OMIM (DLG5 in renal ciliopathies and cystic kidney diseases; and 6 in the proteinuric kidney diseases [APOE, DLC1, FAT1, ITSN1, PODXL and TNS2]) and were excluded." (PMID 40303230, 2025).
diabetic kidney disease (1 paper, 2025). Progressive kidney disorder caused by vascular damage to the glomerular capillaries, in patients with diabetes mellitus. "Since podocytes rely on strongly regulated RhoA signaling to preserve their complex architecture—including foot processes and slit diaphragms—DLC1 upregulation may destabilize the glomerular filtration barrier and promote proteinuria in diabetic kidney disease." (PMID 41306285, 2025).
dilated cardiomyopathy (1 paper, 2025). Cardiomyopathy which is characterized by dilation and contractile dysfunction of the left and right ventricles. "DLC1 is up-regulated in the muscle LIM protein (MLP) knockout mouse, an established model for dilated cardiomyopathy." (PMID 40911671, 2025).
focal segmental glomerulosclerosis (1 paper, 2018). A renal disorder characterized by sclerotic lesions in the glomeruli. "In an individual of Arab descent (A4967-21) with SRNS and a biopsy showing focal segmental glomerulosclerosis (FSGS), we identified two compound heterozygous mutations, p.Glu180Ala and p.Lys1358Thr, in DLC1." (PMID 29773874, 2018).
fracture (1 paper, 2017). "A PPI network was constructed with 167 nodes and 233 edges, and module analysis demonstrated that CCL2, CSF2, NOS2, and DLC1 may stimulate bone overgrowth after femoral fracture via anti-apoptosis-related functions." (PMID 28095896, 2017).
gallbladder cancer (1 paper, 2022). "The restoration of DLC1 expression in gallbladder cancer cells resulted in caspase-3‐mediated apoptosis." (PMID 35223504, 2022).
gastritis (1 paper, 2022). Inflammation of the stomach. "DLC1+ cells were reduced in H. pylori gastritis and GC, and in mice infected with H. pylori." (PMID 35963849, 2022).
hepatic neoplasm (1 paper, 2017). "Age-dependent increase of spontaneous liver neoplasms might result from aging-induced down-regulation of SIRT1 and DLC1." (PMID 28903430, 2017).
malignant meningioma (1 paper, 2016). "To investigate the role of DLC1-v1downregulation we performed a knockdown experiment in KT21 cell line established from human malignant meningioma." (PMID 27614886, 2016). "In our hands, targeting of DLC1-v1 with specific shRNA in KT21cells established from human malignant meningioma resulted in enhanced activity of RhoA/RhoB/RhoC GTPases as shown in active RHO pull down assay and increased cell migration in scratch assay." (PMID 27614886, 2016).
metastatic cancer (1 paper, 2014). A carcinoma which has spread from the original site of growth to another anatomic site. "It expands the known DLC1 role and opens the prospect that DLC1 introduction, or the inhibition of downstream pathways activated by DLC1 deficiency, could sensitize chemotherapy-resistant metastatic cancer to various pharmacological drugs." (PMID 24683532, 2014).
mucinous cystadenocarcinoma (1 paper, 2013). An invasive adenocarcinoma characterized by cystic changes and the presence of malignant glandular cells which contain intracytoplasmic mucin. "Immunohistochemical staining and Western blot were used to examine the expressions of DLC1 and PAI-1 protein in 25 specimens normal ovarian tissues, 52 specimens of serous cystadenocarcinoma tissues and 23 specimens of mucinous cystadenocarcinoma tissues." (PMID 23988121, 2013).
neural tube defect (1 paper, 2020). A congenital defect characterized by failure of the neural tube to close completely; this results in the presence of openings in the brain or spinal cord. "Two out of four previously reported DLC1 nonsense variants were associated with neural tube defect." (PMID 32344861, 2020).
Paget disease (1 paper, 2013). A malignant neoplasm composed of large cells with large nuclei, prominent nucleoli, and abundant pale cytoplasm (Paget cells). "Our previous study showed that DLC-1 methylation significantly correlated with PIK3CA mutations in Paget's disease." (PMID 23509688, 2013).
pancreatic ductal adenocarcinoma (1 paper, 2017). An infiltrating adenocarcinoma that arises from the epithelial cells of the pancreas. "For example, the common hallmark gene DLC1 in several GO terms is an essential gene whose methylation in pancreatic ductal adenocarcinoma tissue samples is significantly associated with the stage, histological differentiation and lymph node metastasis." (PMID 29212244, 2017).
pulmonary hypertension (1 paper, 2015). Increased pressure within the pulmonary circulation due to lung or heart disorder. "As expression levels of p122RhoGAP/DLC-1 were the highest in the lung, our mice may have some phenotypes such as pulmonary hypertension due to enhanced pulmonary arterial vasomotility." (PMID 26624289, 2015).
pyloric stenosis (1 paper, 2014). Narrowing of the pyloric lumen caused either by hypertrophy of the surrounding muscles or tissue scarring due to a chronic peptic ulcer. "In F5 who had cardiac truncus arteriosus, type B interruption of the aortic arch and pyloric stenosis, we found the compound heterozygous mutations c.2189G>A (p.730R>Q) and c.721C>G (p.241P>A) in DLC1 (MIM 604258, ENST00000276297)." (PMID 24476948, 2014).
renal carcinoma (1 paper, 2023). A carcinoma arising from the epithelium of the renal parenchyma or the renal pelvis. "Several RhoGAPs family members, including DLC1 (ARHGAP7), ARHGAP22, ARHGAP24, and ARHGAP29, were reported to play roles in renal cancer." (PMID 37175461, 2023).
T-cell ALL (1 paper, 2009). "DLC1 was hypermethylated in three of six human patients with T-cell ALL." (PMID 19912643, 2009).
T-cell lymphoma (1 paper, 2012). "On the contrary, in our study we have found increased expression of p21waf1 in the heterozygous Dlc1 genetrap allele containing T-cell lymphoma and thymoma cell lines." (PMID 22792269, 2012). "These cell lines have considerably lower level of Dlc1 protein when compared with the corresponding wild type Dlc1 allele containing T cell lymphoma and thymoma cell lines." (PMID 22792269, 2012).
thymic lymphoma (1 paper, 2012). "The Dlc1 deficient thymic lymphoma cell lines exhibited increased trans-endothelial cell migration." (PMID 22792269, 2012). "We established 4 thymic lymphoma (TL) and 3 thymic epithelial carcinoma (TEC) cell lines from the primary tumours to study the expression of Dlc1 protein." (PMID 22792269, 2012).
thymic tumours (1 paper, 2012). "In brief, our finding indicates that Dlc1 isoform 2 undergoes selective hypermethylation in oncogenic K-Ras2 induced thymic tumours and significantly decrease the overall survival in mice." (PMID 22792269, 2012). "The overall frequency of neoplastic lesions and thymic tumours was significantly higher in KD mice suggesting that trapping Dlc1 isoform 2 may have provided an advantage to the initiation of tumourigenesis." (PMID 22792269, 2012). "Thus, our results indicate that in the K-Ras2 induced thymic tumours, selective methylation of the promoter of Dlc1 isoform 2 may lead to a malignant phenotype in thymus." (PMID 22792269, 2012).
thymoma (1 paper, 2012). A neoplasm arising from the epithelial cells of the thymus. "Evidence for differences in function between the Dlc1 isoforms comes from the transfection experiments into the thymoma cell line." (PMID 22792269, 2012).
viral infections (1 paper, 2022). "The overexpression of DLC1 also enhances the tubulins' growth and maintenance to facilitate viral infections." (PMID 35685339, 2022).